TCF4 (transcription factor 4)
Diseases named in the same sentence as TCF4 in open-access papers (continued):
Sharing a sentence is not in itself a finding about the gene and the disease.
colon carcinoma (continued). "pDC development and homeostasis are regulated by the transcription TCF4, which has been reported to be modulated by LPA in colon cancer cells, suggesting that ENPP2 expression from pDCs and the local production of LPA modulates, in an autocrine manner, pDC development and homeostasis." (PMID 34576169, 2021). "Transcription factor TCF4 (T-cell factor 4) is known to be indispensable for tumor initiation and TCF4/β-catenin transcriptional activity mediated by Wnt signaling was proposed to control upregulation of SLC6A14 in colon cancer." (PMID 33195271, 2020). "The weight of evidence indicates that relative expression of PPARβ/δ is not upregulated by APC/β-CATENIN/TCF4 signaling in colon cancer." (PMID 31602402, 2019). "Moreover, inhibiting the β-catenin/TCF4 interaction by a diterpenoid derivative, 15-oxospiramilactone (NC043) induces G2M arrest in colon cancer cells." (PMID 31608135, 2019). "In colon cancers, KLF4 could be down-regulated by caudal type homeobox 2 (CDX2), notch signaling, transcription factor 4 (TCF4) or sex determining region Y-box 9 (Sox9)." (PMID 22937066, 2012). "The chromatin loops are not restricted to colon cancer cells, but are also found in kidney epithelial and lung fibroblast cell lines that lack de-regulated Wnt signaling and nuclear ß-catenin/TCF4 complexes." (PMID 21533051, 2011). "al. demonstrates that Apc-/- colon carcinoma cells contain a stable and constitutively active β-Catenin-TCF4 complex in the nuclei and that reintroduction of APC removes β-Catenin from TCF4 and abrogates the transcriptional activation of TCF4." (PMID 18992165, 2008). "Through interacting with T cell transcription factor-4 (Tcf-4) and beta-catenin, peroxisome proliferator activated receptor gamma (PPAR gamma) may determine colon cell fate and serve as a target of the Wnt pathway in colon cancer cells." (PMID 32117736, 2020). "Furthermore, the gene expression of Wnt and TCF4 was suppressed by the transient expression of TREM2 compared with that in non-transfected or mock-transfected colon cancer cells." (PMID 31489935, 2019). "Moreover, it has been shown in colon cancer that the knockdown of TCF4 rather than knockdown of β-catenin enhances the chemosensitivity of the drugs in inhibiting the cell proliferation and inducing apoptosis." (PMID 31608135, 2019). "The ethanol extract of Hedyotis diffusa Willd could inhibit colon cancer stem cells sphere formation, differentiation in vitro by downregulating the β-catenin and TCF4 mRNA, and inhibiting β-catenin/Wnt pathway and CK20 and CD133 mRNA in colon cancer stem cells, which was time-dose dependent." (PMID 29234398, 2017). "Our aim was to compare the effects of Tcf-4 knockdown and β-catenin knockdown on cell proliferation, apoptosis, and chemosensitivity in the SW480 (mutant APC, wild-type CTNNB1) and HCT116 (mutant CTNNB1, wild-type APC) colon cancer cell lines using short hairpin RNA (shRNA)." (PMID 23029137, 2012). "Thus, the original hypothesis that expression of PPARβ/δ is increased by APC/β-CATENIN/TCF4 signaling in colon cancer is not supported by many subsequent studies." (PMID 31602402, 2019).
Pitt-Hopkins syndrome (97 papers, 2010 to 2026). "Pitt-Hopkins syndrome (PTHS) is a neurodevelopmental disorder caused by haploinsufficiency of the TCF4 gene which encodes the transcription factor 4 protein (TCF4)." (PMID 41509287, 2025). "For example, mutations in CACNA1C and TCF4 are known to cause Timothy syndrome and Pitts-Hopkins syndrome respectively." (PMID 39237719, 2025). "Subsequently, a study utilizing brain organoids to investigate autism (Pitt-Hopkins syndrome) found that specific mutations in transcription factor 4 (TCF4) can disrupt neuronal maturation." (PMID 41359105, 2025). "Prominent evidence is the impaired development of pDCs observed in individuals with Pitt-Hopkins syndrome, caused by TCF4 haploinsufficiency." (PMID 40213544, 2025). "Haploinsufficiency of TCF4 causes Pitt-Hopkins syndrome, a severe NDD associated with ASD, ID, and epilepsy." (PMID 41278953, 2025). "We describe a drug repurposing treatment involving the use of nicardipine in a young patient with Pitt-Hopkins syndrome (a rare neurodevelopmental disorder that results from variants of TCF4 gene) as a bench-to-bedside approach." (PMID 40786031, 2025). "Loss of TCF4 function in Pitt-Hopkins syndrome leads to increased excitability of Nav1.8 in neurons." (PMID 40786031, 2025). "Pitt-Hopkins syndrome (PTHS) is a neurodevelopmental disorder caused by pathogenic variants in TCF4, leading to intellectual disability, specific morphological features, and autonomic nervous system dysfunction." (PMID 38571311, 2024). "Sepp M., Pruunsild P., Timmusk T. Pitt-Hopkins syndrome-associatedmutations in TCF4 lead to variable impairment of the transcriptionfactor function ranging from hypomorphic to dominant-negativeeffects." (PMID 39722673, 2024). "This discovery holds the potential for generating region-specific astrocytes and provides further insights into the neurodevelopmental defects of Pitt-Hopkins syndrome, which is caused by mutations in TCF4." (PMID 39300210, 2024). "Mutations in TCF4 cause Pitt-Hopkins syndrome, a neurodevelopmental disorder characterized by intellectual disability and autistic behavior." (PMID 39300210, 2024). "We concentrated on the gene Tcf4, as its mutation is a cause of Pitt-Hopkins syndrome, and accumulating evidence suggests that Pitt-Hopkins syndrome is associated with aberrant cortical neurons." (PMID 39664574, 2024). "The importance of TCF4 is further underscored by its link to human disorders: deletions or specific mutations in the TCF4 gene cause Pitt-Hopkins syndrome (PTHS, OMIM #610954)." (PMID 39502395, 2024). "Stickler syndrome (N = 2; causative variant in the COL2A1 gene) and Pitt-Hopkins syndrome (N = 3; one causative variant in the TCF4 gene, two cases associated with 18q deletion syndrome) were most common in this cohort." (PMID 39495751, 2024). "Loss-of-function mutations of Tcf4 cause the neurodevelopmental disorder called Pitt Hopkins syndrome and Tcf4 KO mouse models have revealed roles for Tcf4 in the cortex and hippocampus." (PMID 37684687, 2023). "Pitt Hopkins Syndrome (PTHS) is a rare syndromic form of autism spectrum disorder (ASD) caused by autosomal dominant mutations in the Transcription Factor 4 (TCF4) gene." (PMID 36224259, 2023). "Such diversity of functional effects of missense variants has already been shown for other NDDs, for example for TCF4 variants causing Pitt-Hopkins syndrome (MIM #610 954) or variants in UBE3A causing Angelman syndrome (MIM #105 830)." (PMID 34505148, 2022). "TCF4 loss-of-function mutations are the cause of Pitt-Hopkins syndrome (a syndrome causing intellectual disability and behavioral changes amongst other symptoms), and regulatory SNPs relating to TCF4 have been associated with SCZ." (PMID 36344995, 2022). "Some evidence revealed that mutations in the TCF4 gene were associated with Pitt-Hopkins syndrome, a rare mental disease known as mental retardation." (PMID 36193501, 2022).
Pitt-Hopkins syndrome (continued). "Mutations and common polymorphisms within TCF4 have been implicated in several diseases including bipolar disorder, schizophrenia, Pitt-Hopkins Syndrome (OMIM # 610954), and Sonic Hedgehog (SHH) medulloblastoma tumours." (PMID 32735996, 2021). "In humans, inactivating mutations in or loss of TCF4 cause Pitt-Hopkins syndrome in the heterozygous state." (PMID 32266943, 2020). "Loss-of-function mutations in the bHLH transcription factor TCF4 are linked to neurodevelopmental disorders such as intellectual disability and Pitt-Hopkins Syndrome." (PMID 33228529, 2020). "Mutations of TCF4 have been detected in some patients suspected of having Pitt-Hopkins syndrome and Angelman syndrome." (PMID 32280673, 2020). "Pitt-Hopkins Syndrome (PHS) is a sporadic condition caused by disease causing variants or deletions of the TCF4 gene on chromosome 18q." (PMID 31235867, 2019). "In humans, loss of function of Tcf4 leads to the rare neurodevelopmental disorder Pitt-Hopkins syndrome, which is characterized by intellectual disability, developmental delay and autistic behavior." (PMID 29933371, 2018). "Mutations or deletions of the human Tcf4 gene cause Pitt-Hopkins syndrome, a rare developmental disorder which is characterized by severe intellectual disability, developmental delay and autistic behavior." (PMID 29933371, 2018). "In humans, TCF4 haploinsufficiency causes Pitt-Hopkins syndrome, a severe neurodevelopmental disorder, associated with psychomotor delay, intellectual disability, and autistic behavior." (PMID 29588831, 2018). "Molecular and clinical convergence has also been demonstrated between Pitt-Hopkins syndrome (causative gene TCF4) and Kleefstra syndrome." (PMID 29069077, 2017). "Pitt-Hopkins Syndrome (PTHS) is a rare genetic disorder caused by insufficient expression of the TCF4 gene." (PMID 28251008, 2017). "TCF4 mutations also cause Pitt-Hopkins Syndrome, a neurodevelopmental disorder associated with severe mental retardation." (PMID 27752241, 2016). "This deletion contained part of the TCF4 gene and is associated with Pitt-Hopkins syndrome (OMIM # 610954), which is consistent with the referral reason." (PMID 27034718, 2016). "TCF4 is associated with Pitt-Hopkins syndrome (MIM: 610954), which is defined by severe psychomotor delay, epilepsy, daily bouts of diurnal hyperventilation, mild postnatal growth retardation, postnatal microcephaly, and distinctive facial features." (PMID 26491539, 2015). "Mutations in TCF4 cause Pitt-Hopkins syndrome (PTHS); a severe mental retardation syndrome associated with a facial gestalt, breathing abnormalities, visual problems, delayed speech development and seizures." (PMID 24058414, 2013). "In this regard, it is probably significant that haploinsufficiency of TCF4 expression is thought to be causative for Pitt-Hopkins syndrome, a severe form of neurodevelopmental delay." (PMID 23185296, 2012). "Loss-of-function variants in NIPBL cause Cornelia de Lange syndrome; missense variants in ACTG1 lead to Baraitser-Winter syndrome; missense variants in ATP1A3 underlie Snijders Blok-Campeau syndrome; and loss-of-function variants in TCF4 result in Pitt-Hopkins syndrome." (PMID 41300846, 2025). "A SMAD6 variant was associated with premature craniosynostosis and hip dislocation, while TCF4 mutations (Pitt-Hopkins syndrome) produced characteristic facial anomalies, including coarse facial features, a protruding lower face, full cheeks, and cupid’s bow upper lip, in two distinct patients." (PMID 41300846, 2025). "In addition, ablation of TCF4 during mouse development causes neocortical disorganization, which recapitulates structural brain abnormalities present in Pitt-Hopkins syndrome patients." (PMID 35965434, 2022).
Pitt-Hopkins syndrome (continued). "In addition, de novo mutations in one of the TCF4 alleles cause Pitt-Hopkins syndrome —an autism spectrum disorder described by severe cognitive impairment, breathing abnormalities, motor delay, and distinctive facial features." (PMID 36407762, 2022). "We show that Pitt-Hopkins syndrome-associated missense mutations within the basic helix-loop-helix domain of TCF4 and a Rett-like syndrome-associated mutation in a transcription activation domain result in altered DNA-binding and transcriptional activity of the protein." (PMID 34748727, 2021). "Mutations in TCF4 causes Pitt-Hopkins syndrome, a severe neurodevelopmental disorder." (PMID 33462220, 2021). "Given our primary goal to gain first insight how Tcf4 haploinsufficiency, which has been causally linked to neurodevelopmental disorders such as Pitt-Hopkins Syndrome and intellectual disability, affects adult neurogenesis, we analysed constitutive heterozygote Tcf4 knockout mice." (PMID 33228529, 2020). "Importantly, it has previously been shown that point mutations of basic amino acid residues in the bHLH domain of TCF4 were often associated with the Pitt-Hopkins Syndrome." (PMID 31666615, 2019). "Similarly, the clinical features of the patient with the TCF4 variant are found to be consistent with Pitt-Hopkins syndrome upon retrospective review of the patient’s progressive features by the attending physician." (PMID 26666243, 2015). "This p.R580Q TCF4 variant has been reported as pathogenic in patients with Pitt-Hopkins syndrome." (PMID 26666243, 2015). "Mutations or deletions in TCF4 cause Pitt-Hopkins syndrome (PTHS), a rare neurodevelopmental disorder." (PMID 39502395, 2024). "Pitt-Hopkins syndrome (PTHS) is a rare neurodevelopmental disorder with physical, cognitive, and behavioral characteristics that is caused by heterozygous mutations in the TCF4 gene." (PMID 38778377, 2024). "Pitt-Hopkins syndrome (PTHS) is a neurodevelopmental disorder caused by monoallelic mutation or deletion in the transcription factor 4 (TCF4) gene." (PMID 35535852, 2022). "Disordered breathing is a hallmark of Pitt-Hopkins syndrome (PTHS), yet little is known regarding how loss of Tcf4 (gene associated with PTHS) affects development and function of respiratory neurons." (PMID 34645823, 2021). "For example, haploinsufficiency of TCF4 is the main pathogenic mechanism in Pitt-Hopkins syndrome (PTHS), which is characterized by intellectual disability, sensory processing deficits, anxiety, and speech and motor delay." (PMID 32765228, 2020). "Thus, the clinical effects of loss of Tcf4 in Pitt-Hopkins syndrome may, at least in part, also be mediated by the synaptic function of Tcf4." (PMID 29933371, 2018). "Mutations of TCF4, which encodes a basic helix-loop-helix transcription factor, cause Pitt-Hopkins syndrome (PTHS) via multiple genetic mechanisms." (PMID 27179618, 2016). "Pitt-Hopkins syndrome (PTHS) is caused by haploinsufficiency of Transcription factor 4 (TCF4), one of the three human class I basic helix-loop-helix transcription factors called E-proteins." (PMID 26621827, 2015). "Haploinsufficiency of TCF4 causes Pitt-Hopkins syndrome (PTHS): a severe form of mental retardation with phenotypic similarities to Angelman, Mowat-Wilson and Rett syndromes." (PMID 24058414, 2013). "The transcription factor 4 (TCF4) gene is essential for brain development, and its disruption causes Pitt-Hopkins syndrome." (PMID 42238855, 2026). "Chen H.Y., Bohlen J.F., Maher B.J. Molecular and cellular functionof transcription factor 4 in Pitt-Hopkins syndrome." (PMID 39722673, 2024). "In P3, three top performing teams, Team 9 (Invitae Moon), Team 5 (Exomiser), and Team 11 (enGenome), prioritized a de novo variant in TCF4 (c.1228 + 3G > T, ENST00000398339), a disease gene associated with dominant Pitt-Hopkins syndrome (PHS, MIM 610954)." (PMID 38685113, 2024).
Pitt-Hopkins syndrome (continued). "Rescue of behavioral and electrophysiological phenotypesin a Pitt-Hopkins syndrome mouse model by genetic restorationof Tcf4 expression." (PMID 39722673, 2024). "Human KMT2C, MADD and TCF4 are causative genes for three neurodevelopmental disorders, Kleefstra syndrome 2, DEEAH syndrome and Pitt-Hopkins syndrome, respectively." (PMID 37294900, 2024). "However, defects in TCF4 (NM_003199.2) are also causative for Pitt-Hopkins syndrome (PTHS, OMIM #610,954), a multisystem disorder characterized by severe mental retardation, and – in many cases – abnormalities in respiratory rhythm." (PMID 39026379, 2024). "Pitt-Hopkins syndrome (PTHS) is a rare, neurodevelopmental genetic disorder caused by mutations in the TCF4 gene." (PMID 37731434, 2023). "SNPs and somatic mutations in the TCF4 gene are associated with SZ, BD, and ASD, Pitt-Hopkins syndrome (PTHS)." (PMID 36613684, 2022). "The TCF4 gene is responsible for Pitt-Hopkins syndrome, which is characterized by intellectual disability, wide mouth and distinctive facial features, and intermittent hyperventilation followed by apnea (MIM 602272)." (PMID 36393831, 2022). "Embryonic, pan-cellular reinstatement of Tcf4 fully rescues behavioral deficits in a mouse model of Pitt-Hopkins syndrome." (PMID 35535852, 2022). "(A) Schematic depicting a conditional Pitt-Hopkins syndrome mouse model in which expression of the bHLH region of Tcf4 is prevented by the insertion of a loxP-P2A-GFP-STOP-loxP cassette into intron 17 of Tcf4 (Tcf4STOP/+)." (PMID 35535852, 2022). "It therefore is highly unlikely that expansion of CTG18.1 induces TCF4 haploinsufficiency, given the completely different phenotypes associated with FECD and Pitt-Hopkins Syndrome." (PMID 32735996, 2021). "Pitt Hopkins syndrome (PTHS) is a rare and extreme form of ASD that is caused by a pathogenic variant of the TCF4 gene found on chromosome 18q21.2 (11, –, 13)." (PMID 34846164, 2021). "Five patients had pathogenic mutations in the TCF4 gene and one in the UBE3A gene, which are associated with Pitt-Hopkins syndrome and Angelman syndrome, respectively." (PMID 28947817, 2017). "Pitt-Hopkins syndrome (PTHS), caused by a TCF4 gene mutation, is a condition characterized by intellectual disability and developmental delay, breathing anomalies, epilepsy, and distinctive facial dysmorphism." (PMID 27864810, 2016). "Mono-allelic mutations or genomic deletions of TCF4 cause Pitt-Hopkins syndrome (PTHS)." (PMID 27179618, 2016). "Possibly, in this patient, initiation of TCF4 transcription at downstream 5′ exons still takes place, explaining the less severe phenotype than in classical Pitt-Hopkins syndrome patients." (PMID 21789225, 2011). "Together, these findings position mature GABAergic interneurons as the principal site of TCF4 function in the primate neocortex, providing a cellular framework for linking TCF4 dysfunction to cortical circuit imbalance in Pitt-Hopkins syndrome and psychiatric disease." (PMID 42238855, 2026). "Hennig K.M., Fass D.M., Zhao W.-N., Sheridan S.D., Fu T., Erdin S.,Stortchevoi A., Lucente D., Cody J.D., Sweetser D., Gusella J.F.,Talkowski M.E., Haggarty S.J. WNT/β-catenin pathway and epigeneticmechanisms regulate the Pitt-Hopkins syndrome and schizophreniarisk gene TCF4." (PMID 39722673, 2024). "Pitt Hopkins Syndrome (PTHS) is a rare neurodevelopmental disorder resulting from autosomal dominant mutations on chromosome 18 at the TCF4 (also known as ITF2, SEF2, E2-2, not T-cell factor 4 which is encoded by TCF7L2 gene) locus." (PMID 36224259, 2023). "Using a curated list of 484 genes directly implicated in ID (ID Project, University of Colorado Denver) we found two genes: KN Motif And Ankyrin Repeat Domains 1 (KANK1), associated with cerebral palsy, and Transcription factor 4 (TCF4), associated with Pitt-Hopkins Syndrome." (PMID 31288860, 2019).